TNF (tumor necrosis factor)
Diseases named in the same sentence as TNF in open-access papers (continued):
Sharing a sentence is not in itself a finding about the gene and the disease.
cholesteatoma (continued). "Indeed, we found a significantly robust upregulation of the proinflammatory-related genes TNFα, IL1β, IRAK1, p65, NOD2, and a downregulation of IKK2 in cholesteatoma." (PMID 25922834, 2015). "They found a lack of consensus in literature about the localization of TNF-α in cholesteatoma layers." (PMID 17505610, 2007). "Hence the presence of inflammatory mediators in cholesteatoma tissue was studied and exhibits a higher presence of the cytokines TNFα, IL-6, IL-8, IL-1α, and IL-1ß in comparison to non-inflamed external auditory canal skin tissue." (PMID 31947538, 2020). "The difference in TNF-α levels may be related to various other factors such as, for instance, duration of the disease, the intensity of local infection, or the presence and distribution of TNF-α receptors in the cholesteatoma matrix." (PMID 17505610, 2007). "However, the expression and function of TLRs in cholesteatoma remain unclear.We observed inflammatory cell infiltration of the matrix and prematrix of human acquired cholesteatoma, as well as dramatically increased expression of TLR4 and the pro-inflammatory cytokines TNF-α and IL-1β." (PMID 26639190, 2015). "The scRNA-seq data showed that CD45− cells from cholesteatoma did not exhibit upregulation of IL-1β, PGE2 synthase, or TNF-α, compared to skin fibroblasts." (PMID 37537159, 2023).
Giardia infection (16 papers, 2013 to 2025). "TNF-α and IL-6 expressions are elevated during Giardia infection, their deficiency facilitates delayed elimination of the parasite." (PMID 35482821, 2022). "Another study reported that children with symptomatic giardiasis had increased mucosal levels of pro-inflammatory cytokines, including TNFα." (PMID 36232855, 2022). "Certainly, TNF-α has a very important role in the early control of giardiasis, as previously demonstrated in Giardia infection using mouse models." (PMID 36232855, 2022). "Another study in mice proposed a protective role of this pro-inflammatory cytokine in giardiasis since animals devoid of TNFα showed that peak Giardia load levels were around 10-fold higher compared with control mice." (PMID 36232855, 2022). "It was reported that Giardia infection can enhance the production of proinflammatory cytokines, such as TNF-α, IFN-γ, IL-6, and IL-12 p40 in PMs, through the TLR2-mediated activation of MAPK signaling." (PMID 34943932, 2021). "Proinflammatory chemokines, including TNF-α, and B lymphocyte activating interleukins, such as IL-4 and IL-5 belong to the chemokine profile described in Giardia infection." (PMID 34778111, 2021). "The proinflammatory cytokines TNF-α and IL-6 are essential for the elimination and early control of giardiasis in mice." (PMID 34336841, 2021). "The protective role of TNF, a major cytokine of M1 macrophages, has been reported in Mycobacterium tuberculosis, Candida albicans and Giardia lamblia infections, in which it limits pathogen persistence and improves survival of mice." (PMID 34987498, 2021). "A positive correlation was observed between I-FABP and IL-17 levels as well as TNF, suggesting that epithelial damage can be related to cytokine production during giardiasis." (PMID 31861618, 2019). "Some studies show that individuals with giardiasis have TNF-α and IL-2 high, similar to Th1 response." (PMID 29541642, 2018). "On the other hand, the atrophy of intestinal villi and dysfunction of the gut epithelial barrier detected in biopsy specimens from chronically infected patients with giardiasis can also be observed when healthy intestinal biopsy specimens are treated with TNFα." (PMID 36232855, 2022). "In addition, recent studies have established that immune-mediated apoptosis induced by Fas or TNF-α is responsible for increased epithelial permeability in giardiasis." (PMID 34208266, 2021). "Furthermore, IL-6 and TNF-α are known to be involved in the elimination and early control of Giardia infection." (PMID 34336841, 2021). "Our measurement of IL-6 and TNF-α serum levels showed higher levels in infected untreated animals compared to uninfected ones, which is in line with studies which demonstrated major roles of these cytokines in controlling giardiasis." (PMID 34208266, 2021). "TNF-α-deficient mice do not appear to be related to mechanisms previously shown to control Giardia infections, including IgA production, mast cell responses, IL-6 or IL-4 expression." (PMID 28979269, 2017). "Hence, the affectation on epithelial integrity during giardiasis might be due to parasite factors such as GlADI and host-defense factors such as TNFα." (PMID 36232855, 2022). "First we studied cytokines that earlier have been shown to be up-regulated during Giardia infections in mice, i.e. IL-1, IL-2, IL-4, IL-5, IL-9, IL-10, IL-12, IL-17a, IL-17c, IFN-γ, TGF-β, and TNF-α." (PMID 34335577, 2021). "Untreated Giardia-infection may regulate innate and adaptive immune responses mediated by Th17 CD4+T cells and induction of Th1, Th2 and Th17 cytokines, including IL-2, IL-5, IL-6, IL-8, IL-12, IL-13, IL-23, IFN-γ and TNF-α." (PMID 30412580, 2018). "We found that TLR2−/− mice did not affect TNF-α and IL-6 production in vivo, while AKT-blocked mice did increase the production of these two cytokines during Giardia infection." (PMID 28979269, 2017).
Giardia infection (continued). "AKT-blocked macrophage in vitro enhanced the production of IL-12 p40, TNF-α, and IL-6 but not IFN-γ, while the AKT inhibitor still enhanced IFN-γ production in vivo in response to Giardia infection." (PMID 28979269, 2017). "In addition, macrophages from TLR2−/− mice in vitro showed enhanced production of IL-12 p40, TNF-α, and IL-6 but not IFN-γ, while TLR2−/− mice only showed enhanced production of IL-12 p40 and IFN-γ in vivo in response to Giardia infection." (PMID 28979269, 2017).
hypoadiponectinemia (16 papers, 2014 to 2025). "Experimental studies proved that adiponectin expression is negatively regulated by pro-inflammatory cytokines, including IL-6 and TNF-α, whereas adiponectin modulates the action and production of TNF-α in various tissues, while hypoadiponectinemia is associated with increased IL-6 levels." (PMID 33738273, 2020). "It depends on both IL-6 and TNF-a, with high serum concentrations related to hypoadiponectinemia and, consequently, to a low anti-inflammatory response." (PMID 37585909, 2023). "CuE also ameliorated adipose tissue dysfunction by reducing hyperleptinemia and TNF-alpha levels and enhancing hypoadiponectinemia." (PMID 28598969, 2017). "Visceral obesity results in hypoadiponectinemia and an increase in tumor necrosis factor-α, interleukin (IL)-6, and other adipokines, which in turn result in insulin resistance." (PMID 28887474, 2017). "HFD mice also exhibited hypoadiponectinemia and increased serum levels of interleukin-6 (IL-6) and tumor necrosis factor (TNF)-α compared with ND mice." (PMID 26518260, 2015). "Accordingly, marked hypoadiponectinemia and augmented TNF-α levels detected in the serum of the HFHF group contributed to stimulating the main clinical features of MS as IR and consequently hepatic steatosis, which can be ascribed to adiponectin anti-inflammatory and anti-lipogenic effects." (PMID 36418417, 2022). "An indirect correlation observed between adiponectin and TNF-α in the current study could be addressed that hypoadiponectinemia in GDM results in increased levels of TNF-α." (PMID 29387323, 2018). "Therefore, as the antagonist of adiponectin, the TNF-α-induced activation of proinflammatory cytokines and hypoadiponectinemia with glucose intolerance can assist in distinguishing patients with NASH from those with simple steatosis." (PMID 27563875, 2016). "Also, hypoadiponectinemia related to systemic inflammation may have a role in the development of NAFLD because adiponectin has anti-inflammatory effects via inhibition of tumor necrosis factor (TNF)-α and IL-6." (PMID 30673698, 2019). "Therefore, a therapy combining anti-TNF-α and anti-lymphotoxin alpha could restore APN serum levels in patients with hypoadiponectinemia verified in cases of IRS." (PMID 32876087, 2020).
insulinoma (16 papers, 2010 to 2025). "For instance, isolated polyphenols of rosemary, such as carnosic acid and rosmarinic acid, were shown to cause an increase in TNFα and nitrate levels leading to the induction of apoptosis in rat insulinoma (RINm5F) cells." (PMID 32795297, 2020). "IFN-γ induces the expression of IRF-1, which makes insulinoma cells susceptible to TNF-α." (PMID 21113299, 2010). "This is because a high level of TNF-α in insulinoma cells will raise the concentration of Ca2+cytosolic, which in turn stimulates calpain and calcineurin." (PMID 34639164, 2021). "Treatments that induced ATF3 activation and IRS2 suppression included induction of apoptosis by combined treatment of insulinoma cells with γ-interferon, TNF-α, or the ER stress activator thapsigargin." (PMID 21541314, 2011). "Conversely, low‐dose TNF‐α in tumour blood vessel normalisation substantially promotes the infiltration of cytotoxic lymphocytes and was thereby shown to improve anti‐tumour vaccination or adoptive T‐cell therapy in a pre‐clinical model of insulinoma." (PMID 37132170, 2023). "Similarly, miR-21, miR34a, and miR-146a increased significantly through the induction of IL-1β and TNF-α in mouse insulinoma 6 (MIN6) cells." (PMID 33233727, 2020). "One possible mechanism is a C21-mediated decrease in TNF-α, since TNF-α is known to induce apoptotic cell death in mouse primary β cells and insulinoma cell lines, and inhibit glucose-stimulated insulin transcription and secretion observed in the HIT-T15 pancreatic β cell line." (PMID 23155382, 2012). "β-cell apoptosis is induced when tumor necrosis factor α or IL-1β, along with IFN-γ, is applied to human and animal islets and insulinoma cells." (PMID 39968090, 2025). "Previous reports showed that caffeic acid enhanced glucose uptake in tumor necrosis factor α-treated insulin-resistant FL83B cells and human skeletal muscle cells (SkMC C-12580), and increased insulin secretion in rat insulinoma cells (INS-1E)." (PMID 30841887, 2019). "In addition, PRDX6 protected rat insulinoma RIN-m5F β cells, cultured with TNF-α and IL-1β, against the cytokine-induced cytotoxicity and reduced the apoptotic cell death and production of ROS." (PMID 32908936, 2020). "By exposing NIT1 insulinoma cells and rat islets to a cocktail of pro-inflammatory cytokines (TNFα and IL1β), we mimicked inflammatory signaling as seen by JNK and NFκB activation and increased mRNA levels of TNFα, IL1β and NOS2a." (PMID 24974801, 2014). "Moreover, the amplitude of high-voltage-activated Ca2+ currents has been demonstrated to be increased in MIN6N8 insulinoma cells exposed to IFN-γ and TNF-α, resulting in an increase in cytosolic Ca2+ concentration and activation of calpain and calcineurin." (PMID 21113299, 2010). "Moreover, the GPR40 agonists could reduce inflammatory signaling, such as NF-κB, IL-1β, TNF-α, and NOS2α, in the mouse NIT1 insulinoma cells and rat islets that are under chronic inflammatory conditions and LPS-induced activation of IKK in BV2 cells." (PMID 30981281, 2019). "It was previously reported that Bcl-2 was not significantly influenced by TNF-α and IFN-γ treatment of MIN6 insulinoma cells." (PMID 25811609, 2015).
intestinal infection (16 papers, 2010 to 2025). "The challenge of healthy adult male volunteers with attenuated ETEC prevented intestinal infection upon a secondary challenge with the same bacteria, and this protective effect was associated with improved productions of TNF-α and IL-6 by blood monocytes." (PMID 40141330, 2025). "Many studies have shown that Th1 cytokines, such as IL-12, INF-γ, IL-1β, and TNF-α are much more abundant in the early stages of intestinal infection by T. spiralis." (PMID 38166140, 2024). "Studies found that lactobacilli with the ability to reduce the severity of intestinal infections can improve the phagocytic activity of macrophages and their capacity to produce inflammatory factors such as TNF-α and IFN-γ." (PMID 37431006, 2022). "With the TNF inhibitor adalimumab, compared to the 0.4 mg/kg study arm (8%; gastrointestinal infection, hand fracture, agitation), while it was low in the 0.8 mg/kg study arm (0%)." (PMID 36226155, 2022). "This study also looked into the production of TNF-α, a pleiotropic proinflammatory cytokine expressed in many human diseases including gastrointestinal infection." (PMID 34367513, 2021). "Soon after intestinal infection S. enterica induces a significant increase in the expression of IL-17 and related cytokines such as TNF-α, IL-1β, IL-6 and IL-23." (PMID 24340048, 2013). "There were less gastrointestinal tract infections observed in the TNF-alpha inhibitor group." (PMID 30658717, 2019). "With an exception of gastrointestinal tract infections, the risk of developing these infections is elevated in patients treated with TNF-alpha inhibitor, but the relationship is not significant." (PMID 30658717, 2019). "Because local production of TNF-α appears to be responsible for synovial inflammation induced during S. Enteritidis intestinal infection, we analyzed whether consumption of the probiotic modifies the production of this inflammatory molecule." (PMID 24340048, 2013). "It is unknown, however, how TNF-α directly modulates bacterial protein expression during intestinal infection and chronic inflammation." (PMID 20704730, 2010). "In the situation of intestinal infection, JNK inhibition resulted in reductions of c-Jun expression and significant suppression of proinflammatory cytokines such as IL-1β, IL-6, and TNF-α." (PMID 33281910, 2020). "Intestinal infection with this pathogen elicits a TH1-biased immune response, characterized by the induction of IFN-γ and TNF-α." (PMID 30818341, 2019).
lactic acidosis (16 papers, 2009 to 2025). Metabolic acidosis characterized by the accumulation of lactate in the body. "For example, in ruminants, preliminary findings showed that lactic acidosis (lowered pH and increased faecal lactate) was significantly associated with increased tumor necrosis factor-alpha (TNF-α)." (PMID 28592308, 2017). "M1 microglia produce pro-inflammatory cytokines such as IL-1β, TNF-α, and IL-6, which trigger the inflammatory response and cause damage such as mitochondrial oxidative phosphorylation, lactic acidosis, and excessive accumulation of free radicals, leading to neuronal necrosis." (PMID 40944219, 2025). "Anti-TNFα agents currently represent a real opportunity for these patients while bone marrow transplantation needs to be considered carefully taking into consideration the risk of complications including those correlated to severe lactic acidosis." (PMID 35984545, 2023). "The administration of recombinant TNF-α in animal models led to the appearance of fever, lactic acidosis, hemodynamic changes, and even death." (PMID 22482045, 2012). "Changes of plasma levels of TNF-α, IL-6, troponin-I, ALT, AST and urea following severe lactic acidosis in pigs." (PMID 23326542, 2013). "When a small quantity of endotoxin was injected into humans, increased levels of TNF-α were noted, while the administration of recombinant TNF-α in animal models led to the appearance of fever, lactic acidosis, hemodynamic changes, and even death." (PMID 22482045, 2012). "Previous paper reported that GSTP1 promoted the S-glutathionylation of SRC under TNF-α stimulation, but is not found under lactic acidosis in our paper." (PMID 37491277, 2023). "In the absence of stimulation, FACS-sorted day 3 LA-Mφ with and without depolarized mitochondria had similar levels of IL-6 and TNFα mRNA, higher in both cases than those in Mφ not exposed to lactic acidosis." (PMID 34880237, 2021).
myeloproliferative neoplasm (16 papers, 2010 to 2025). A clonal hematopoietic stem cell disorder, characterized by proliferation in the bone marrow of one or more of the myeloid (i.e., granulocytic, erythroid, megakaryocytic, and mast cell) lineages. "In both situations, the absence of such proteins resulted in the development of myeloproliferative diseases; interestingly, in the case of retinoid acid deficiency, transplanting total BM from TNF-α KO into retinoic acid receptor deficient mice protected these from myeloproliferative disease." (PMID 20126546, 2010). "Increased platelet mitochondrial mass was observed in patients with myeloproliferative neoplasms and increased tumor necrosis factor-α (TNF-α)." (PMID 34582480, 2021). "The authors concluded that TNF-α is one of the mechanisms involved in BM malignant transformation, particularly in the case of myeloproliferative disease." (PMID 20126546, 2010). "Key to Rux efficacy is its broad anti-inflammatory activity against the myeloproliferative neoplasm (MPN) inherent cytokine storm with pro-inflammatory IL-1, IL-6, IL-8, IL-12, TNF-α, IFNγ, VEGF, TGFβ, FGF, PDGF, GM-CSF, and G-CSF cytokines/growth factors." (PMID 32518419, 2020). "Myeloproliferative neoplasm (MPN) is a chronic hematologic malignancy characterized by chronic inflammation, high TNFα levels in serum, activation of NFĸB and reduced expression of XIAP." (PMID 31908904, 2020). "For instance, recent works shows that the secretion of inflammatory cytokines such as tumor necrosis factor‐α (TNF‐α), from bone marrow stromal cells contributes to immune dysregulation and the selective proliferation of JAK2V617F+ clones in myeloproliferative neoplasms." (PMID 39254117, 2024). "Given that elevated TNFα levels and NFĸB activation is a characteristic feature of myeloproliferative neoplasms (MPN), we investigated the effect of the SMAC mimetic LCL-161 on MPN cell survival in vitro and disease development in vivo." (PMID 31908904, 2020).